CHEK2 (checkpoint kinase 2)
Diseases named in the same sentence as CHEK2 in open-access papers (continued):
Sharing a sentence is not in itself a finding about the gene and the disease.
tumor (continued). "We further show that three chemicals predicted to functionally substitute for SOD1 silencing also induce preferential killing within BLM- and CHEK2-deficient cells in short (5-day), moderate (14-day) and long-term (28-days) assays in both 2D culture and 3D tumor models." (PMID 26318585, 2015). "Cells with the c.470T>C variant of CHEK2 exhibit no response to DNA damage, although a synergistic effect with deficiency of CHEK2 in tumor cells may also be induced by drugs that target microtubules (e.g., taxanes)." (PMID 26083025, 2015). "However, functional loss of CHEK2 may be directly involved in potentiating the immune response through canonical inflammatory and anti-tumor pathways, acting through the cGAS-STING pathway." (PMID 40492861, 2025). "Given CHEK2’s established role in cell cycle checkpoint control and genomic stability, this elevated OR could point to an influence on the more proliferative LB phenotype, which is typically associated with higher tumor grade and Ki-67 expression." (PMID 40507526, 2025). "Interestingly, when we evaluated the tumor-in-tumor pattern to investigate clonal evolution, we found that the CHEK2 p.(Tyr390 Cys) likely pathogenic variant was present in the high-grade areas of two tumors (IB and II), one of which subsequently developed a lymph node metastasis." (PMID 40448797, 2025). "As such, CHEK2 germline alterations may contribute to oncogenesis through the inability to activate DNA damage repair pathways and/or the accumulation of additional genetic variants, leading to tumor formation and metastasis." (PMID 36980535, 2023). "Notably, IC-011 spheroid derives from a tumor characterized by a CHEK2 inactivating mutation." (PMID 33407715, 2021). "However, the presence of many variants of unknown significance (VUS) with a specific population prevalence prevents precise assessment of the risk associated with particular tumor types in CHEK2 mutation carriers." (PMID 33322746, 2020). "Specific CHEK2 germline variants may have a distinct impact on tumor biology." (PMID 31360903, 2019). "Thus, it is possible that 2ME2, ATTM or LCS-1 treatments in BLM- or CHEK2-deficient/defective tumors may induce anti-angiogenic effects that will synergize with the SL interactions to prevent tumor vascularization while inducing SL killing." (PMID 26318585, 2015). "Since CHEK2 plays a key role in the DNA damage pathway, loss of function of the protein may allow cells to evade normal cell cycle checkpoints, ultimately leading to tumour initiation or progression." (PMID 21569354, 2011). "In Case 1, the mutation profiles of the two tumor lesions shared only a PDGFRA and DNMT3A missense mutation and a CHEK2 frameshift mutation." (PMID 40589631, 2025). "Through phosphorylation of numerous substrates, CHEK2 regulates cell cycle arrest, DNA repair and apoptosis upon DNA damage, thus acting as a tumour suppressor (e.g)." (PMID 41152984, 2025). "This review explores two possible explanations for this observed phenomenon: the first relating to the canonical role of CHEK2, and the second introducing a novel role of the CHEK2 gene in immunomodulation of the tumor microenvironment (TME)." (PMID 40492861, 2025). "In this review, we explore the effect of CHEK2 alterations on the tumor immune microenvironment, both within and beyond the DDR pathway." (PMID 40492861, 2025). "Patient tumors harboring DDR mutations, including 1100delC CHEK2 mutants and/or BRCA1/2 deleterious variants, showed higher percentages of tumor shrinkage (ORR = 86%) and longer overall survival (PFS = 30 months)." (PMID 40492861, 2025).
tumor (continued). "Tumor cells with low CHEK2 displayed enrichment of type I interferon in the TME and a subsequently higher PD-L1 expression induced by IFN-γ." (PMID 40492861, 2025). "For example, the protein product of CHEK2 responds to DNA damage and replication blocks, playing a role as a cell cycle checkpoint regulator and a putative tumor suppressor." (PMID 40416963, 2025). "CHEK2 (Checkpoint Kinase 2) encodes a DDR kinase (CHK2); its loss can raise tumor mutational burden and activate cGAS–STING, while high CHEK2 expression has been linked to weaker benefit from immune checkpoint inhibitors." (PMID 41154602, 2025). "CHEK2 gene encodes for the checkpoint kinase 2 (CHK2), an effector serine/threonine kinase with critical role in cell cycle regulation, functioning as a tumor suppressor." (PMID 41457124, 2025). "This aligns with the established biological role of CHEK2 in maintaining genomic integrity through cell cycle regulation, a function critically compromised in aggressive, genomically unstable tumor types such as TNB." (PMID 40507526, 2025). "The CHEK2 gene serves as a tumor suppressor, is vital for controlling cell cycle checkpoints, initiating DNA repair processes, and promoting apoptosis." (PMID 39624521, 2024). "Among the rest, one tumor each had a ETV6-NTRK3 fusion, a PTEN deletion, an FGFR1 gain-of-function mutation, a CHEK2 LOF mutation (T367fs*), an AURKA-CSTF1 fusion, and a FANCA deletion." (PMID 38730662, 2024). "In total, 13 of 97 patients (13%) carried a germline (likely) pathogenic variant in a well-known tumor predisposition gene: APC (n = 1), BRCA2 (n = 2), CHEK2 (n = 4), DICER1 (n = 4), HOXB13 (n = 1), and MITF (n = 1)." (PMID 38415346, 2024). "Tumor sequencing revealed LOH in CHEK2 and PALB2, as well as CCND1,FGFR1, GPR124, ZNF217, ZNF703, and PTPN1 amplifications." (PMID 38091153, 2024). "These off‐tumor incidental findings are not only common in moderately penetrant genes such as CHEK2, but have been described for highly‐penetrant genes such as BRCA1/2, as well." (PMID 38898688, 2024). "In total, 13 patients (13%) carried a P/LP variant in a known autosomal dominant tumor predisposition gene: APC (n = 1), BRCA2 (n = 2), CHEK2 (n = 4), DICER1 (n = 4), HOXB13 (n = 1), and MITF (n = 1)." (PMID 38415346, 2024). "In conclusion, the study findings implicate CHEK2 as a candidate susceptibility gene for DFSP and provide a rationale for future epidemiologic and functional studies to evaluate this gene-tumor relationship more completely." (PMID 39669616, 2024). "Still, CHEK2 c.1100delC carriers have a shorter survival and intrinsic tumor aggressiveness plays a role." (PMID 37161532, 2023). "This scRNA-seq data also showed enrichment of “Interferon type I response pathway” (p = 2.8e−13) in low CHEK2 expressing tumor cells as compared to the high CHEK2 expressing tumor cells." (PMID 36949040, 2023). "The combination of Chek2 inhibition therapy with oncolytic viral therapy can also be a rational approach, based on the premise that Chek2 depleted tumor cells perhaps resembled virus-infected cells, in the context of induction of type I interferon response." (PMID 36949040, 2023). "CHEK2 c.1100delC carriers were diagnosed at younger age and in earlier calendar years, both for the first primary tumor as well as for the CBC." (PMID 36824750, 2023). "We analyzed 7930 cells and stratified tumor cells as expressing high or low levels of CHEK2 using the median as cutoff value." (PMID 36949040, 2023). "T cells from the low CHEK2 expressing tumor cells showed gene ontology (GO) term enrichment for “Interferon γ (IFN-γ) signaling” as compared to the T cells from high CHEK2 expressing tumor cells (p = 0.0005)." (PMID 36949040, 2023).
tumor (continued). "Within this tumor, the deletion of the long arm of chromosome 22 effectively resulted in reduction to homozygosity of the NF2 frameshift variant but loss of the CHEK2 mutant allele, resulting in enhanced representation of the wild-type allele in the tumor." (PMID 36980535, 2023). "Previous studies suggested that CHEK2 is the tumor suppressor that exerts its effect by postponing the progression of the cell cycle, thus facilitating DNA repair." (PMID 38081888, 2023). "Further, we analyzed another independent scRNA-seq dataset to assess the phenotype of the tumor cell in the context of CHEK2 expression." (PMID 36949040, 2023). "First, the expression levels of CHEK2 in different tumor types in the TIMER database were evaluated." (PMID 38081888, 2023). "Further, the T-cell compartment associated with the low CHEK2 expressing tumor cells showed significant enrichment in pathway related to T-cell proliferation (p = 5.1e−17) as compared to the T cells from high CHEK2 expressing tumor cells." (PMID 36949040, 2023). "In a study of patients with tumor CGP-identified mutations in moderate risk breast and ovarian CSGs (ATM, BRIP1, CHEK2, PALB2, RAD51C, and RAD51D), 24% of patients with germline variants would not have met criteria for germline testing." (PMID 37568048, 2023). "The present work focused on evaluating the expression of CHEK2 and its prognostic value in ccRCC patients, as well as its correlation with immune properties in the tumor microenvironment (TME)." (PMID 38081888, 2023). "On the tumor-cell compartment, the low CHEK2 expressing tumor cells showed GO term enrichment for “Interferon type I response” as compared to the tumor cells from high CHEK2 expressing tumor cells (p = 0.032)." (PMID 36949040, 2023). "Clinical, tumor and treatment characteristics for the first primary BC by CHEK2 c.1100delC carrier status." (PMID 37401034, 2023). "BC genomes from CHEK2 mutation carriers were most similar to ER+ BC genomes and least similar to those of BRCA1/2 mutation carriers in terms of tumor mutational burden as well as mutational signatures." (PMID 37161532, 2023). "Massive DNA sequencing of the WBC (germ line) revealed a pathogenic mutation in CHEK2 and the complete loss of a VHL allele (both tumour suppressors)." (PMID 37843608, 2023). "Carrier probabilities for CHEK2 now show a decline with age for ER-negative tumours (previously, this was only predicted for ER-positive disease)." (PMID 36162851, 2022). "The presence of the CHEK2 c.1100delC mutation in DNA derived from her PCC and archival PCC tumor tissue was subsequently determined." (PMID 36440216, 2022). "CHEK2 (checkpoint kinase 2; MIM# 604373) is a tumor suppressor gene that encodes a serine threonine kinase involved in pathways such as DNA repair, cell cycle arrest, mitosis, and apoptosis." (PMID 35885426, 2022). "Tumor mutational burden (TMB) was 20.22 mutations/Mb and germline frameshift mutation of CHEK2 was detected." (PMID 35794571, 2022). "The p.R137* mutation occurred in the functionally important domain of CHEK2 (the FHA domain), resulting in the loss of the protein kinase domain and promoting tumor formation." (PMID 35281821, 2022). "The IHC images in the Human Protein Atlas also demonstrate that CHEK2 was overexpressed in tumor tissues." (PMID 35300428, 2022). "Lastly, in the results of IHC for CHEK2 expression, tumor or normal adrenal tissue, stromal cells, such as vascular endothelial cells, were not stained positive." (PMID 34630562, 2021).
tumor (continued). "One of the key tumor-suppressor genes involved in cell cycle checkpoint control, DNA damage response signaling, and the regulation of apoptosis and cell aging is checkpoint kinase 2 (CHEK2)." (PMID 33530461, 2021). "The natural PTOX analog 4′-demethyl-deoxypodophyllotoxin glucoside (4DPG), which increased the expression of checkpoint kinase 2 (Chk2), a tumor suppressor of the DNA damage checkpoint pathway." (PMID 34447752, 2021). "RB1 and CHEK2 act as tumor suppressors, maintaining the cell in G1, whereas CCNE1 (cyclin E1) acts as an oncogene when mutated or abnormally activated." (PMID 33396315, 2020). "Four variants showed LOH in the tumor specimen (ATM c.4709T>C; CHEK2 c.1036C>T; PALB2 c.1001A>G, and RAD50 c.281T>C), which is an indication of pathogenicity." (PMID 33134171, 2020). "Four variants of uncertain significance showed loss of heterozygosity in the tumor (ATM c.4709T>C; CHEK2 c.1036C>T; PALB2 c.1001A>G, and RAD50 c.281T>C), which is an indication of pathogenicity." (PMID 33134171, 2020). "Animal experiments with Chek2 knockout (Chk2-/-) mice demonstrated that Chk2-/- mice are viable and fertile, developing a slightly increased tumor incidence with a long latency, and that they are more radioresistant compared with wild type Chk2 mice." (PMID 33322746, 2020). "CHEK2 gene at position 12.1(22q12.1) provides instructions for making checkpoint kinase 2 proteins as a tumor suppressor." (PMID 30975222, 2019). "CHEK2 also acts as a tumor suppressor by promoting genomic stability, enabling DNA repair, and inducing apoptosis." (PMID 29682443, 2018). "We tested eleven distinct mutations in several genes, including the oncogenes ERBB2 and VEGFR2 and the tumor suppressors CHEK2 and TGFBR1." (PMID 28743916, 2017). "Checkpoint kinase 2 (Chk2) is a universal tumor suppressor gene that is activated in response to various genotoxic threats including ionizing radiation (IR) or chemotherapies." (PMID 29062040, 2017). "The tested mutations are from four genes, including two tumor suppressors (TGFBR1 and CHEK2) and two oncogenes (KDR and ERBB2)." (PMID 28743916, 2017). "In this study, we found that both highly recurrent (CHEK2 K373E) and rare point mutations (CHEK2 S372F/Y and A392V, TGFBR1 S241L and L354P) in tumor suppressors can also cause loss- or reduction-of-function." (PMID 28743916, 2017). "This notion is supported by genes such as the checkpoint kinase 2 (CHEK2) and tuberin, which have been described as tumor suppressors; or CSF3R which has been described as an oncogene." (PMID 27150584, 2016). "In vitro studies suggested that tumor cells with silenced CHEK2 expression showed an increased sensitivity to the PARP 1 inhibitor." (PMID 25884806, 2015). "For example, BLM and CHEK2 are somatically altered in a number of tumor types including CRC, and normally function within the homology directed repair (HDR) pathway (“error-proof” DSB repair pathway)." (PMID 26318585, 2015). "Although CHEK2*1100delC homozygous female carriers are more susceptible to tumor development, analysis of tumors from CHEK2*1100delC heterozygous carriers show a heterogeneous pattern of LOH/loss at the CHEK2 locus." (PMID 26553136, 2015). "BLM and CHEK2 are two evolutionarily conserved genes that are somatically altered in a number of tumor types." (PMID 26318585, 2015). "CHEK2 plays an important role in cell cycle regulation and DNA damage repair, processes that are central in prevention of tumor development." (PMID 16539695, 2006). "There are thus good arguments for why this modification changing a lysine to glutamate might be activating in CHEK2 despite its role as a tumour suppressor." (PMID 41152984, 2025).
tumor (continued). "Moreover, deficit mutations in checkpoint kinase 2 (CHEK2), an important gene in the DDR, enhance the antitumor effect of anti-PD-1 therapy, as shown in mice with MC38 and B16 tumors, by affecting the tumor immunological microenvironment." (PMID 39941003, 2025). "As proven in the present study, the list of genes from the 44-gene panel more frequently mutated in BOT compared to the other tumor groups (FANCB, SEM1, FANCA, BRCA2, CHEK2, MUTYH, RAD50) was much longer than analogically altered genes in the hot-spot panel (KRAS only)." (PMID 39456660, 2024). "The first BOADICEA prediction model integrated the risk due to the rare loss-of-function variants in the “major genes” (BRCA1 and 2, PALB2, CHEK2 and ATM) with tumor pathology (receptors status), basic demographic element (e.g., year and country of birth and family ethnicity), and family history." (PMID 38397209, 2024). "In addition, one tumor each had a NTRK3 fusion (ETV6-NTRK3), a PTEN deletion, an FGFR1 GOF mutation (K654E), a CHEK2 LOF mutation (T367fs*), and an Aurora kinase A fusion (AURKA-CSTF1)." (PMID 38730662, 2024). "Tumor sequencing revealed LOH in CHEK2 and ATM, as well as CCND1 and GAB2 amplifications." (PMID 38091153, 2024). "According to The Cancer Genome Atlas Research, in addition to hereditary predisposition to the development of PTC, somatic mutations occur in the CHEK2 gene, which may contribute to PTC tumor progression." (PMID 38398207, 2024). "One patient had a VUS in both BRCA2 and CHEK2 genes in her tumor." (PMID 37173992, 2023). "In numerous phase II and III clinical studies, little or no response to multiple PARPi was reported in diverse tumor types carrying HR mutations in genes such as CHEK2, ATM, FANCA, and CDK12." (PMID 37761329, 2023). "CHEK2 appeared to be primarily expressed in macrophages and tumor cells of the human GBM specimens." (PMID 36949040, 2023). "Furthermore, tumours showing homologous recombination deficiency, due to loss of BRCA1, BRCA2, PALB2 and CHEK2 function, have been shown to be especially sensitive to platinum-based chemotherapeutics and PARP inhibition." (PMID 36831687, 2023). "We identified germline CHEK2 variants in 2% of our pediatric/young adult cohort, with no clear discernment toward a particular tumor type." (PMID 36980535, 2023). "One patient had ATM and CHEK2 mutations identified in ctDNA drawn 7 months after tumor molecular testing without these alterations." (PMID 36933202, 2023). "Additionally, CHEK2 affects tumor immune cell infiltration and the immunotherapeutic response, which possibly predicts a poor prognosis of ccRCC." (PMID 38081888, 2023). "A negative association was observed between tumor intrinsic Chek2 expression and IFN-γ signaling and cytotoxicity of T cells." (PMID 36949040, 2023). "This suggested that tumor intrinsic Chek2 may be regulating resistance to CD8 T-cell-mediated cytotoxicity." (PMID 36949040, 2023). "Given its biological role, it is not unexpected that genetic studies have implicated CHEK2 as a multiorgan tumor susceptibility gene." (PMID 36360192, 2022).